KAT5 (lysine acetyltransferase 5)
Description:
Catalytic subunit of the NuA4 histone acetyltransferase complex, a multiprotein complex involved in transcriptional activation of select genes principally by acetylation of nucleosomal histones H2A and H4. Histone acetylation alters nucleosome-DNA interactions and promotes interaction of the modified histones with other proteins which positively regulate transcription. The NuA4 histone acetyltransferase complex is required for the activation of transcriptional programs associated with proto-oncogene mediated growth induction, tumor suppressor mediated growth arrest and replicative senescence, apoptosis, and DNA repair. The NuA4 complex plays a direct role in repair of DNA double-strand breaks (DSBs) by promoting homologous recombination (HR): the complex inhibits TP53BP1 binding to chromatin via MBTD1, which recognizes and binds histone H4 trimethylated at 'Lys-20' (H4K20me), and KAT5 that catalyzes acetylation of 'Lys-15' of histone H2A (H2AK15ac), thereby blocking the ubiquitination mark required for TP53BP1 localization at DNA breaks. Also involved in DSB repair by mediating acetylation of 'Lys-5' of histone H2AX (H2AXK5ac), promoting NBN/NBS1 assembly at the sites of DNA damage. The NuA4 complex plays a key role in hematopoietic stem cell maintenance and is required to maintain acetylated H2A.Z/H2AZ1 at MYC target genes (By similarity). The NuA4 complex is also required for spermatid development by promoting acetylation of histones: histone hyperacetylation is required for histone replacement during the transition from round to elongating spermatids (By similarity). Component of a SWR1-like complex that specifically mediates the removal of histone H2A.Z/H2AZ1 from the nucleosome. Directly acetylates and activates ATM. Promotes nucleotide excision repair (NER) by mediating acetylation of ERCC4/XPF, thereby promoting formation of the ERCC4-ERCC1 complex. Relieves NR1D2-mediated inhibition of APOC3 expression by acetylating NR1D2. Acts as a regulator of regulatory T-cells (Treg) by catalyzing FOXP3 acetylation, thereby promoting FOXP3 transcriptional repressor activity. Involved in skeletal myoblast differentiation by mediating acetylation of SOX4. Catalyzes acetylation of APBB1/FE65, increasing its transcription activator activity. Promotes transcription elongation during the activation phase of the circadian cycle by catalyzing acetylation of BMAL1, promoting elongation of circadian transcripts (By similarity). Together with GSK3 (GSK3A or GSK3B), acts as a regulator of autophagy: phosphorylated at Ser-86 by GSK3 under starvation conditions, leading to activate acetyltransferase activity and promote acetylation of key autophagy regulators, such as ULK1 and RUBCNL/Pacer. Acts as a regulator of the cGAS-STING innate antiviral response by catalyzing acetylation the N-terminus of CGAS, thereby promoting CGAS DNA-binding and activation. Also regulates lipid metabolism by mediating acetylation of CHKA or LPIN1. Promotes lipolysis of lipid droplets following glucose deprivation by mediating acetylation of isoform 1 of CHKA, thereby promoting monomerization of CHKA and its conversion into a tyrosine-protein kinase. Acts as a regulator of fatty-acid-induced triacylglycerol synthesis by catalyzing acetylation of LPIN1, thereby promoting the synthesis of diacylglycerol. In addition to protein acetyltransferase, can use different acyl-CoA substrates, such as (2E)-butenoyl-CoA (crotonyl-CoA), S-lactoyl-CoA (lactyl-CoA) and 2-hydroxyisobutanoyl-CoA (2-hydroxyisobutyryl-CoA), and is able to mediate protein crotonylation, lactylation and 2-hydroxyisobutyrylation, respectively. Acts as a key regulator of chromosome segregation and kinetochore-microtubule attachment during mitosis by mediating acetylation or crotonylation of target proteins. Catalyzes acetylation of AURKB at kinetochores, increasing AURKB activity and promoting accurate chromosome segregation in mitosis. Acetylates RAN during mitosis, promoting microtubule assembly at mitotic chromosomes. Acetylates NDC80/HEC1 during mitosis, promoting robust kinetochore-microtubule attachment. Catalyzes crotonylation of MAPRE1/EB1, thereby ensuring accurate spindle positioning in mitosis. Catalyzes lactylation of NBN/NBS1 in response to DNA damage, thereby promoting DNA double-strand breaks (DSBs) via homologous recombination (HR). (Microbial infection) Catalyzes the acetylation of flavivirus NS3 protein to modulate their RNA-binding and -unwinding activities leading to facilitate viral replication.
Synonyms: Tip60; HTATIP; PLIP; cPLA2; HTATIP1; ESA1; NEDFASB; TIP; ZC2HC5
Tractability: Small molecule: a structure with a bound ligand is known; a high-quality ligand is known; it has a high-quality binding pocket. PROTAC: UniProt records ubiquitination sites on it; ubiquitination databases record sites on it; its protein half-life has been measured; a small molecule that binds it is known.
Target class: Epigenetic regulator; Writer; Histone acetyltransferase; MYST family
Gene: Protein-coding gene on chromosome 11 (65,711,996 to 65,719,604, forward strand). Ensembl gene ENSG00000172977.
Subcellular location: Nucleus; Chromosome; Cytoplasm; Chromosome, centromere, kinetochore; Cytoplasm, cytoskeleton, spindle pole; Nucleus, nucleolus; Cytoplasm, perinuclear region
Subcellular location (Human Protein Atlas): Nucleoplasm; Cytosol; Vesicles
Pathways (Reactome):
DNA Repair: HDR through Homologous Recombination (HRR); HDR through Single Strand Annealing (SSA); Homologous DNA Pairing and Strand Exchange; Nonhomologous End-Joining (NHEJ); Presynaptic phase of homologous DNA pairing and strand exchange; Processing of DNA double-strand break ends; Recruitment and ATM-mediated phosphorylation of repair and signaling proteins at DNA double strand breaks; Resolution of D-loop Structures through Holliday Junction Intermediates; Resolution of D-loop Structures through Synthesis-Dependent Strand Annealing (SDSA); Sensing of DNA Double Strand Breaks
Disease: Defective HDR through Homologous Recombination Repair (HRR) due to PALB2 loss of BRCA1 binding function; Defective HDR through Homologous Recombination Repair (HRR) due to PALB2 loss of BRCA2/RAD51/RAD51C binding function; Defective homologous recombination repair (HRR) due to BRCA1 loss of function; Impaired BRCA2 binding to PALB2; Impaired BRCA2 binding to RAD51
Signal Transduction: Estrogen-dependent gene expression; Formation of the beta-catenin:TCF transactivating complex
Cell Cycle: G2/M DNA damage checkpoint
Cellular responses to stimuli: DNA Damage/Telomere Stress Induced Senescence
Chromatin organization: HATs acetylate histones
Developmental Biology: Cardiogenesis
Gene Ontology:
Molecular function: chromatin binding; DNA-binding transcription factor binding; histone acetyltransferase activity; histone H2A acetyltransferase activity; histone H2AK5 acetyltransferase activity; histone H4 acetyltransferase activity; histone H4K16 acetyltransferase activity; peptide 2-hydroxyisobutyryltransferase activity; peptide butyryltransferase activity; peptide crotonyltransferase activity; peptide lactyltransferase (CoA-dependent) activity; protein binding; protein-lysine-acetyltransferase activity; transcription coactivator activity; acetyltransferase activity
Biological process: cellular response to estradiol stimulus; cellular response to glucose starvation; DNA damage response; DNA repair-dependent chromatin remodeling; double-strand break repair; double-strand break repair via homologous recombination; establishment of mitotic spindle orientation; lipid droplet disassembly; negative regulation of DNA-templated transcription; negative regulation of double-strand break repair via homologous recombination; negative regulation of interleukin-2 production; negative regulation of transcription by RNA polymerase II; nucleotide-excision repair; positive regulation of aggrephagy; positive regulation of attachment of mitotic spindle microtubules to kinetochore; positive regulation of autophagy; positive regulation of DNA-templated transcription; positive regulation of double-strand break repair via homologous recombination; positive regulation of mitotic sister chromatid segregation; positive regulation of myoblast differentiation; positive regulation of regulatory T cell differentiation; positive regulation of transcription by RNA polymerase II; positive regulation of triglyceride biosynthetic process; and 18 more
Cellular component: chromatin; chromosome; cytoplasm; kinetochore; mitotic spindle pole; NuA4 histone acetyltransferase complex; nucleolus; nucleoplasm; nucleosome; nucleus; piccolo histone acetyltransferase complex; site of double-strand break; Swr1 complex; histone acetyltransferase complex; perinuclear region of cytoplasm; spindle pole; transcription regulator complex
Genetic constraint (gnomAD): Loss-of-function variants: 31 observed, 70.44 expected, observed/expected ratio (o/e) 0.44, 90% interval 0.33 to 0.59. The synonymous counts are far from expectation, so gnomAD's model fits this gene poorly and the ratio says little. Missense variants: 451 observed, 727.9 expected, observed/expected ratio (o/e) 0.62, 90% interval 0.57 to 0.67. Synonymous variants: 365 observed, 299.6 expected, observed/expected ratio (o/e) 1.22, 90% interval 1.12 to 1.33.
Homologues: Orthologues: rat Kat5 (99% identical), dog KAT5 (99% identical), chimpanzee KAT5 (93% identical), macaque KAT5 (93% identical), mouse Kat5 (93% identical), guinea pig KAT5 (93% identical), rabbit KAT5 (86% identical), pig KAT5 (75% identical), Drosophila melanogaster d4 (8% identical), Caenorhabditis elegans dpff-1 (7% identical), Drosophila melanogaster tth (6% identical). Paralogues in human: KAT6B (38% identical), KAT6A (37% identical), KAT7 (33% identical), KAT8 (32% identical), RSF1 (15% identical), PHF10 (11% identical), DPF1 (11% identical), DPF3 (11% identical), DPF2 (10% identical).
Diseases named in the same sentence as KAT5 in open-access papers:
KAT5 is named in the same sentence as 121 diseases in open-access papers, as found by Europe PMC text mining. Sharing a sentence is not in itself a finding about the gene and the disease. The quoted sentences say what the papers report.
breast carcinoma (45 papers, 2009 to 2026). "KAT5 was shown to acetylate the key EMT-inducing transcription factor (EMT-TF) Twist to promote transcription of EMT genes in vitro in basal-like breast cancer cells HEK293 and SUM1315." (PMID 40165290, 2025). "Ketamine inhibits proliferation and promotes ferroptosis and apoptosis of breast cancer cells via targeting KAT5 KAT5/H3K27a/GPX4 axis." (PMID 35333774, 2022). "Using data from 8 independent breast cancer cohorts (cBioPortal33, n = 3627) the overall rate of Kat5 gene amplification was observed to be 1.6% (n = 58)." (PMID 30846725, 2019). "Exploring the relationship between Kat5 expression and overall survival (OS) in breast cancer, low Kat5 expression significantly correlated (p = 0.0071) with reduced OS (n = 1402)." (PMID 30846725, 2019). "Investigating the difference in Kat5 expression between normal (n = 76) and breast cancer (n = 6547) samples, a significant difference was found (p = 0.0000000332) [median 453 (range 84–1205) v 605 (range 11–2125)]29." (PMID 30846725, 2019). "KAT5, a HAT of the MYST family, has been identified as a haploinsufficient tumor suppressor, and loss or low expression of KAT5 was observed in a fraction of breast cancer cases, correlating with poor prognosis." (PMID 40165290, 2025). "This indicates that the role of KAT5 in breast cancer is complex and context dependent." (PMID 40165290, 2025). "Moreover, it has been reported that Ketamine inhibits proliferation and promotes ferroptosis of by targeting KAT5/GPX4 signaling in breast cancer cells." (PMID 35685642, 2022). "Examining individual breast cancer subtypes, low Kat5 expression significantly correlated with decreased RFS in all subtypes: Luminal A (n = 1933; p = 0.00014), Luminal B (n = 1149; p = 0.000054), Her2 positive (n = 251; p = 0.00062) and Basal (n = 618; p = 0.011)." (PMID 30846725, 2019). "Interestingly, diacetylation of TWIST by KAT5 resulted in an active TWIST complex at the Wnt5a promoter in basal-like breast cancer." (PMID 29449840, 2018). "Consistent with this, Tip60 (KAT5), which belongs to the MYST acetyltransferase family, was recently reported to contribute to a reduction of H3K4 acetylation in breast cancer and the decrease of Tip60 expression could promote the tumorigenesis of ER-negative tumors." (PMID 33193750, 2020). "The lysine acetyltransferase 5 (KAT5) inhibitor ketamine reduces H3K27ac levels in the GPX4 promoter region, which boosts ferroptosis from breast cancer." (PMID 40327848, 2025). "In this context, ketamine, an inhibitor of lysine acetyltransferase 5 (KAT5), reduces H3K27ac levels at GPX4 promoter regions to promote ferroptosis in breast cancer." (PMID 39595619, 2024). "Inhibition of lysine acetyltransferase 5 (KAT5), which reduces H3K27ac abundance at the GPX4 promoter, downregulates GPX4 and promotes ferroptosis in breast cancer cells." (PMID 39568772, 2024). "Ketamine, an inhibitor of lysine acetyltransferase 5 (KAT5), inhibits GPX4 by decreasing the levels of H3K27ac, leading to the execution of ferroptosis in breast cancer." (PMID 38392340, 2024). "Lidocaine induces the ferroptosis of ovarian and breast cancers by increasing miR-382-5p and decreasing SLC7A11, while ketamine induces ferroptosis by targeting the KAT5/GPX4 axis in breast cancer cells." (PMID 35805124, 2022). "Examining the correlation between low Kat5 expression and Relapse Free Survival (RFS) in breast cancer a significant correlation (p = 0.000000084) was seen (n = 3951)." (PMID 30846725, 2019). "In basal-like breast cancer, the TWIST protein, a well known EMT inducer, is specifically diacetylated by KAT5 to interact with BRD4 and activate WNT5A." (PMID 27581651, 2016).
breast carcinoma (continued). "Lastly, in radioresistant subpopulations of breast cancer cells induced by irradiation, ATM, a protein activated by KAT5 acetylation, is hyperactivated and mediates stabilization of ZEB1, another well known EMT inducer, in breast cancer and other types of solid tumours." (PMID 27581651, 2016). "Moreover, as a result of the direct relationship between KAT5 and ATM kinase, our findings may highlight the critical role of the DNA damage response (DDR) in tumorigenesis and metastasis in the basal subtype of breast cancer." (PMID 27581651, 2016). "Another study showed that low expression of KAT5 led to decreased H3K4 acetylation and knockdown of KAT5 promoted the progression of MDA-MB-231 xenografts, a TNBC model, but not MCF-7 xenografts, an ER-positive breast cancer model." (PMID 40165290, 2025).
prostate carcinoma (28 papers, 2009 to 2025). A carcinoma that arises from epithelial cells of the prostate gland. "Reduced KAT5 expression was significantly associated with high mortality in prostate cancer patients." (PMID 31489246, 2019). "The pathogenic effect of KAT5 in prostate cancer was observed in our previous study." (PMID 34390329, 2021). "KAT5 can induce prostate cancer cells’ apoptosis and suppress their growth, representing a gene therapy target." (PMID 34390329, 2021). "Herein, decreased KAT5 expression in prostate cancer tissues was observed and KAT5 upregulation promoted circSMARCA5 production." (PMID 34390329, 2021). "Previous studies have shown that KAT5 expression is reduced in the cytoplasm of the prostate cancer cell line LNCaP when exposed to androgen." (PMID 31489246, 2019). "In this study, we found that KAT5 expression was significantly reduced in prostate cancer tissues and cell lines." (PMID 31489246, 2019). "Here, we showed that KAT5 expression was significantly reduced in prostate cancer tissues and cell lines by using the public databases Oncomine and Human Protein Atlas." (PMID 31489246, 2019). "TIP60/KAT5 is up-regulated in prostate cancer and its impact on nuclear translocation following AR acetylation has been reported." (PMID 28486411, 2017). "Another study shows a metastatic suppression function of KAT5 in a prostate cancer model highlighting the fact that EMT regulation is strongly tissue dependant." (PMID 27581651, 2016). "For instance, KAT5 negatively regulated the growth of prostate cancer cells." (PMID 35383533, 2022). "Functionally, KAT5 suppression enhanced the migrative and invasive capabilities and reversed the circSMARCA5 suppressive effects, suggesting a novel link of the KAT5-mediated circSMARCA5 production in prostate cancer." (PMID 34390329, 2021). "Therefore, KAT5-mediated circSMARCA5 biogenesis suppressed prostate cancer invasive, migrative, and progressive capabilities, in vitro and in vivo." (PMID 34390329, 2021). "Our previous study focused on KAT5's effects on prostate cancer pathogenesis." (PMID 34390329, 2021). "Furthermore, ectopic KAT5 expression significantly induced the apoptotic cell death of prostate cancer cells." (PMID 31489246, 2019). "Moreover, KAT5 has been reported to have a role in the molecular pathway leading to androgen-independent prostate cancer after long-term androgen deprivation therapy." (PMID 31489246, 2019). "Although, much remains to be elucidated regarding the molecular mechanisms of KAT5 in prostate cancer initiation and progression, the correlation of low KAT5 expression with a higher chance of tumor aggressiveness suggest that KAT5 is an attractive biomarker of prostate cancer." (PMID 31489246, 2019). "Moreover, low levels of endogenous KAT5 in the prostate cancer cell line were closely related with the low expression of apoptosis-related proteins in the same cell line." (PMID 31489246, 2019). "Taken together, KAT5 induced apoptosis in prostate cancer cells via the caspase-3 pathway, indicating that KAT5 could be a gene therapy target for prostate cancer." (PMID 31489246, 2019). "Here, we showed that KAT5 negatively regulates the growth of prostate cancer cells, suggesting that KAT5 could be a therapeutic candidate for prostate cancer therapy." (PMID 31489246, 2019). "Moreover, one study also demonstrated that KAT5 or KAT6B knockdown could suppress the AKT/AKT signaling in prostate cancer cells." (PMID 35383533, 2022). "Moreover, it has been reported that ASP metabolite salicylate represses KAT5 and MUC1 to inhibit epithelial to mesenchymal transition in prostate cancer cells, but the effect of ASP on KAT5 and the association of KAT5 with PD-L1 remain unclear." (PMID 35392432, 2022).